CRP (C-reactive protein)
Diseases named in the same sentence as CRP in open-access papers (continued):
Sharing a sentence is not in itself a finding about the gene and the disease.
COVID-19 (continued). "Another study showed that patients experiencing COVID-19-related cardiac injury with the elevated levels of troponin T (TnT) also demonstrated significantly higher CRP and procalcitonin levels (up to 3–4 times more) and experienced increased morbidity and mortality." (PMID 32754159, 2020). "In particular, multivariable regression revealed that older age, TnI levels greater than 0.03 μg/L, CRP levels greater than 10 mg/L, and a respiratory rate over 24 times per minute were associated with increasing odds of ICU admission in COVID-19 patients with underlying CVD." (PMID 32765943, 2020). "Elevated CRP levels have been a consistent finding in COVID-19 patients." (PMID 32397399, 2020). "Reports suggests that the hyperinflammation seen in severe COVID-19 may be driven by considerable levels of C-reactive protein (CRP) and Interleukin (IL)-6, resembling “cytokine storms” seen in other comparable conditions such as during CAR T cell therapy." (PMID 33303843, 2020). "Additionally, our results showed that the AUC of AEC on admission for predicting ICU transfer among elderly COVID-19 patients was 0.828, nearly equivalent to that of CRP and ferritin." (PMID 33251234, 2020). "This observational study tracks changes in HRV relative to changes in CRP in COVID-19 patients." (PMID 33206183, 2020). "With following parameters such as age > 52 years, C-reactive protein > 64.79 mg/L, lactate dehydrogenase > 245 U/L, D-dimer > 0.96 μg/mL, serum amyloid A > 100.02 mg/L, or albumin < 36 g/L, the progress of COVID-19 to critical stage should be closely observed and possibly prevented." (PMID 32677918, 2020). "Older age, CRP greater than 10 mg/L, TnI higher than 0.03 μg/L, and respiratory rate over 24 times per minute were associated with increasing odds of ICU admission in COVID-19 patients with CVD." (PMID 32765943, 2020). "In univariate analysis, high WBC, NLR, CRP, fibrinogen, D-dimer, creatine kinase and LDH, and low lymphocyte were not only risk factors for severity but also risk indicators for death among patients with COVID-19." (PMID 32805722, 2020). "Univariate analysis showed that the erythrocyte count, hemoglobin count, neutrophil count, lactate dehydrogenase, CK-MB, troponin I, procalcitonin, CRP, IL-6, and IL-10 may be factors that affect the severity of COVID-19." (PMID 33192519, 2020). "The data obtained by the chi-squared test showed that patient age >40 years, combined with basic diseases, decreased peripheral blood lymphocyte percentage and count, increased C-reactive protein level, and increased blood sedimentation were all factors related to COVID-19 severity (all P < 0.05)." (PMID 32802219, 2020). "Indeed, elevated neutrophil products have been identified in the sera of COVID-19 patients and correlate with clinical parameters such as C-reactive protein, D-dimer, and lactate dehydrogenase." (PMID 32943497, 2020). "All hospitalized pediatric patients diagnosed with COVID-19 should undergo the following laboratory tests on admission: blood count with reticulocytes, inflammatory markers (CRP, ESR, IL-6, ferritin), prothrombin time, activated partial thromboplastin time (APTT), fibrinogen, and D-dimer." (PMID 33331400, 2020). "An updated meta-analysis by Soraya and Ulhaq define crucial laboratory parameters that can be used in COVID-19 diagnosis and prognosis, indicating that higher leukocyte counts, neutrophils, D-dimer, and CRP positively correlates with severe COVID-19 when compared to non-severe cases." (PMID 32714336, 2020). "Older age and higher levels of C-reactive protein, procalcitionin, interleukin-6, and lactate might predict COVID-19 progression." (PMID 33239109, 2020). "Other studies also reported elevated levels of CRP in COVID-19 patients in Wuhan." (PMID 33187475, 2020). "Moreover, the AUC of AEC in predicting ICU transfer for elderly COVID-19 patients was equivalent to that of CRP and ferritin." (PMID 33251234, 2020).
COVID-19 (continued). "The findings of this study indicated that the integration of NLR and CRP may lead to improved predictions and is recommended as a valuable early marker to assess prognosis and evaluate the severity of clinical symptoms in COVID-19 patients." (PMID 33244379, 2020). "Recent studies have reported that CRP levels are elevated in patients with COVID-19 and may correlate with severity of disease and disease progression." (PMID 33216774, 2020). "In addition, the elevated levels of CRP observed in the present study, as well as in previous studies, also suggest that there is a persistent inflammatory response in COVID-19 patients." (PMID 33256643, 2020). "The increase of CRP was observed in COVID-19 and influenza groups compared to healthy controls." (PMID 33148349, 2020). "Additionally, we found that hypertension, lymphopenia and high CRP predicted for the development of stage IIB COVID-19." (PMID 32864192, 2020). "Recent studies have reported that low lymphocyte-to-C-reactive protein ratio and CRP could be predictive biomarkers for COVID-19 severity." (PMID 33244379, 2020). "In addition, patients with severe COVID-19 had higher serum lactate dehydrogenase (indicating tissue damage), C-reactive protein peaks (indicating inflammation) and lower counts of infection-fighting lymphocytes than those with milder disease." (PMID 33066765, 2020). "Pro-inflammatory neutrophils and CRP may be one of the factors that make the cancer patients more serious and have a poor prognosis after being infected with COVID-19." (PMID 33192519, 2020). "Age; temperature; anorexia; and white blood cell count, neutrophil percentage, platelet count, lymphocyte count, C-reactive protein, aspartate transaminase, creatine kinase, albumin, and fibrinogen values were significantly different between patients with mild and severe COVID-19 (P < 0.05)." (PMID 32571410, 2020). "In regard to the hematological parameters, COVID-19 patients showed decreased erythrocyte count, hemoglobin, hematocrit, lymphocyte count, eosinophil count, and complement C1q, whereas neutrophils, C-reactive protein, and procalcitonin were significantly increased, especially in severe cases." (PMID 32669467, 2020). "In order to further clarify whether elevated troponin could also be used as a predictor for early identification of severe COVID-19, we used Pearson’s correlation analysis to analyze the correlation between cardiac troponin I (cTnI) and CRP and LDH." (PMID 33334317, 2020). "The level of CRP was also higher for patients with COVID-19 in some clinical cases." (PMID 33055059, 2020). "The elevations in hs-TnI/T are also associated with elevated levels of NT-ProBNP and C-reactive protein (CRP), suggesting the myocardial injury observed in COVID-19 patients may be linked with ventricular dysfunction and inflammation." (PMID 33195487, 2020). "Therefore, while discovering the same results, we further analyzed the dynamic changes of pro-inflammatory neutrophils and CRP, and further verified that the pro-inflammatory neutrophils and CRP were adverse effects in cancer patients with COVID-19." (PMID 33192519, 2020). "Eosinopenia combined with elevated CRP could also be used to facilitate the rapid identification of highly suspected COVID-19 patients." (PMID 32724668, 2020). "Thus, we selected leukopenia, eosinopenia, and low procalcitonin levels along with high CRP levels as useful routine blood tests for the diagnosis of COVID-19." (PMID 33208116, 2020). "However, our study showed that LDH had a higher prognostic accuracy than lymphocyte and a similar accuracy as CRP for predicting the in-hospital mortality in severe and critically ill patients with COVID-19." (PMID 32922185, 2020). "In this study, we tracked HRV and CRP changes in 16 COVID-19 patients." (PMID 33206183, 2020). "Investigations revealed hyponatraemia, raised CRP, and positive for COVID-19." (PMID 32433817, 2020).
COVID-19 (continued). "As a result, serum lymphocytes (OR:0.2, 95% CI:0.04-0.96, P < 0.05), CRP (OR:1.026, 95% CI:1.006-1.046, P < 0.05), and LDH (OR:1.009, 95% CI:1.002-1.016, P < 0.05) were found to be independent risk factors for the severity of COVID-19 patients." (PMID 32633729, 2020). "In this study, 22% of the patients presented with an increased CRP level at the time of admission, which suggested that an increase in the CRP level may occur at an early stage of COVID-19." (PMID 33275609, 2020). "A meta-analysis of laboratory findings of clinical characteristics for COVID-19 patients found that the pooled frequency of anemia from two studies was 44% (95% CI, 30%–58%), while the pooled frequency for high C-reactive protein (CRP) from eight studies was 72% (95% CI, 54%–85%)." (PMID 32492787, 2020). "Prior to CT findings, CRP increased at the early stage of severe COVID-19." (PMID 33304910, 2020). "Another systematic review including 11 case reports of COVID-19 patients indicated that tocilizumab could effectively inhibit the hyper-inflammatory state by downregulating the level of IL-6 and CRP level." (PMID 34765999, 2020). "Early detection of elevations in serum CRP, combined with a clinical COVID-19 symptom presentation may be used as a surrogate marker for the presence and severity of the disease." (PMID 32574328, 2020). "In plasma collected from 175 patients who had recovered from mild COVID-19, NAb and S-binding-antibody titers correlated positively with age and CRP (C-reactive protein) levels, but negatively with lymphocyte counts; and the NAbs did not cross-neutralize SARS-CoV-1." (PMID 32573433, 2020). "Additionally, the proinflammatory markers IL-6, ferritin, LDH and CRP, drawn on admission or on day of COVID-19 diagnosis for patients already hospitalized at the time of positive PCR, were associated with higher odds of intubation by univariate analysis." (PMID 33351817, 2020). "Our analysis identified several factors associated with worsening clinical status in adults with COVID-19: fever, cough, dyspnea, pneumonia, any pathological CT findings, any GGO, lymphocytopenia, elevated CRP, elevated ALT and AST, increasing age and male sex." (PMID 32941548, 2020). "In this study, we provided evidences that inflammation reflected by cytokine storms and CRP in COVID-19 patients could have contributed to disease worsening." (PMID 32475230, 2020). "Diminished risk of severe COVID-19 in ARB-treated patients Lower concentrations of CRP and procalcitonin in ACEi/ARB treated patients ≥ 20 registered clinical trials: CAPTOCOVID (NCT04355429), RAMIC (NCT04366050), NCT04345406 (capto/enalapril), NCT04355936 (telmisartan)." (PMID 32848769, 2020). "In patients with COVID-19 however there are increased levels of fibrinogen, CRP, and D-dimer, with elevated D-dimer levels being a risk factor for mortality these findings indicate that there appears to be an increase not only in coagulation but also in fibrinolysis." (PMID 33042029, 2020). "Furthermore, our study expands the observations showing that COVID-19 patients with CVD had higher levels of CRP." (PMID 32765943, 2020). "Thus, this study aims to assess whether significant alterations in erythrogram indicators and CRP levels in ICU patients with acute respiratory syndrome related to COVID-19 can serve as effective prognostic biomarkers for severe outcomes." (PMID 40362375, 2025). "Although some studies demonstrated an increase in creatine metabolite levels, similar to inflammatory markers such as CRP and IL-6, in patients with COVID-19, our study indicated that fluctuating creatine levels in patients in the ICU could be predictive of different prognostic outcomes." (PMID 40608744, 2025). "Similarly, retrospective series show elevated CRP, ferritin, and neutrophil counts are more frequent in COVID-19 patients who develop AKI, and recent data confirm that inflammatory biomarkers correlate with early-onset AKI and non-recovery in critical COVID-19." (PMID 41462971, 2025).
COVID-19 (continued). "In our study, patients with SARS-CoV-2 infection had lower levels of inflammatory markers such as CRP, procalcitonin, and IL-6 compared to non-COVID-19 patients, suggesting that reduced inflammatory burden may contribute to the higher cholesterol and LPC levels observed in this group." (PMID 41007672, 2025). "This indicates that elevated C-reactive protein levels are associated with an increased risk of death, confirming that severe systemic inflammation, as reflected by elevated C-reactive protein values, may contribute to a poorer prognosis among elderly patients with COVID-19." (PMID 40141715, 2025). "Moreover, while inflammatory (e.g., CRP, IL-6) and coagulation (e.g., D-dimer) markers may mediate the relationship between chronic diseases and COVID-19 mortality, our study prioritized variables routinely documented in clinical practice." (PMID 40463970, 2025). "However, these markers have not yet shown a consistent association with the risk of in-hospital mortality, unlike CRP, which can be used as a mortality biomarker in patients with greater frailty and worse prognosis in COVID-19." (PMID 40362375, 2025). "In the progression phase, patients with COVID-19 present higher levels of CRP than those in a stable state, and its measurement at 7 days of hospitalization has been found to be a reliable marker to evaluate the response to treatment in patients with moderate or severe COVID-19." (PMID 39859366, 2025). "Unlike CRP, MR-proADM reflects microvascular leakage, which is a hallmark of severe COVID-19." (PMID 40559088, 2025). "Similarly, C-reactive protein (p = 0.0267) and urea (p = 0.0027) showed higher mean values of 5.81 mg/L and 42.45 mg/dL, respectively, in individuals with moderate COVID-19 compared to those with critical COVID-19." (PMID 39861879, 2025). "Therefore, in the current study, we investigated three independent biomarkers, CRP, leucocyte cell count, and suPAR, to determine whether they could predict long-term pulmonary function impairment as part of long COVID-19 among survivors." (PMID 40095788, 2025). "In COVID-19 acute respiratory distress syndrome (ARDS), lipidomic analysis of tracheal aspirates revealed distinct lipid changes associated with VAP, with sphingomyelin (34:1) and PC (O-34:1) outperforming C-reactive protein (CRP) and procalcitonin (PCT) as biomarkers." (PMID 41011521, 2025). "The systemic inflammatory response observed in acute COVID-19, characterized by elevated levels of cytokines, such as IL-2, IL-10, IL-6, IL-8, C-Reactive Protein (CRP), and Tumor Necrosis Factor (TNF)-alpha, triggers acute phase reactions and, if sustained, may lead to end-organ damage." (PMID 40029921, 2025). "Elevated levels of C-reactive protein indicate severe systemic inflammation, which may worsen the patients’ condition and contribute to a poor prognosis, particularly in the context of serious conditions such as COVID-19." (PMID 40141715, 2025). "Among non-COVID-19 hospitalized patients, the primary reasons for admission were heterogeneous; however, the presence of lymphopenia, anemia, hypoalbuminemia, and elevated CRP in patients with indeterminate QFT-Plus results reflected the severity of their illness." (PMID 40690446, 2025). "Moreover, elevated CRP levels in COVID-19 patients support the hypothesis that persistent inflammation plays a role in atherosclerosis progression." (PMID 41012624, 2025). "Moreover, CRP remained unchanged over the time point in long COVID-19 cohort." (PMID 40335840, 2025). "When looking at COVID-19 specific factors, infection prior to 2021 compared to July-December 2021, and symptom duration 8–10 days compared to less than 5 days, NIV/HFNC, eGFR < 60, higher N-Ag quanterix, higher CRP, and D-dimer > 0.93 were associated with D0 lymphopenia." (PMID 39810077, 2025).
COVID-19 (continued). "Moreover, COVID-19 patients with co-infections exhibited even higher levels of IL-6, CRP, and PCT, suggesting that bacterial co-infections may amplify the inflammatory response and worsen patient outcomes." (PMID 40046064, 2025). "CRP levels may serve as a useful clinical biomarker for guiding corticosteroid therapy, and in the near future, emerging insights into the immunomodulatory mechanisms of corticosteroids in COVID-19 may help identify corticosteroid-responsive phenotypes." (PMID 40598558, 2025). "Additionally, it was positively correlated with C-reactive protein in T2D and COVID-19 patients, suggesting that the F/B ratio may be a potential biomarker for inflammation in these patients." (PMID 39598083, 2024). "However, when tocilizumab is applied, the use of CRP as an indicator of its activity is especially useful due to its accessibility, low cost, and its close relationship to the modulation of the inflammatory status in hospitalized patients due COVID-19." (PMID 38687065, 2024). "Also, COVID-19 patients tended to have higher levels of CRP and IL-6." (PMID 38246829, 2024). "In our study, participants with PASC, as defined by self-reported symptoms, had raised CRP at 6 months after COVID-19 onset when adjusting for age, sex, comorbidities (including obesity) at COVID-19 onset, initial COVID-19 severity, dexamethasone treatment and recent COVID-19 vaccination." (PMID 39008486, 2024). "The exact role of CRP in COVID-19 pathogenesis remains unclear and requires further research." (PMID 39195007, 2024). "The research of COVID-19 patients revealed laboratory measures, including an average white blood cell count that was higher than normal, a platelet count that was within the predicted range, raised C-reactive protein levels, probable tissue damage, ferritin levels, and D-Dimer levels." (PMID 39273719, 2024). "Furthermore, s100b concentration displayed significant correlations with inflammation markers (such as ferritin, C-reactive protein, and procalcitonin) as well as indicators of organ damage (such as alanine aminotransferase and creatinine) in acute COVID-19 populations." (PMID 38541055, 2024). "The IL-6 cytokine serves as a marker for COVID-19 severity, showing a negative correlation with age in patients infected with the Delta variant and a positive correlation with CRP, COVID-GRAM score, total leukocyte count, and neutrophils in those infected with the Omicron variant." (PMID 39281077, 2024). "Therefore, this research may contribute to further our understanding of the role of IL-6, ferritin, C-reactive protein, hepcidin, and zinc in COVID-19 patients residing at different altitudes." (PMID 39062181, 2024). "Also, the severity of COVID-19 is associated with elevated inflammatory markers, such as increased WBC counts, elevated CRP and ferritin levels, leukocytosis, neutrophilia, elevated D-dimer and procalcitonin, as well as CT findings of bilateral patchy shadows or ground glass opacity." (PMID 39458141, 2024). "It was observed that the levels of inflammatory serological markers such as C-reactive protein and procalcitonin, classically associated with bacterial infections, may also rise in COVID-19-affected individuals in the absence of bacterial co-infections." (PMID 39458151, 2024). "At a median of 6-months following admission, 18 (42 %) of the COVID-19 patients had died and independent predictors of death (Odd Ratio: Confidence Intervals) were age (1.18: 1.06‒1.37), Troponin level (Log 10 transformed) (16.54: 2.30‒266.65) and C-Reactive Protein (CRP) (1.30: 1.10‒1.65)." (PMID 39197405, 2024). "In our study, elevated CRP and PCT levels were associated with higher risk of DKA or HHS in T2DM with COVID-19 infection, confirming that a hyper-inflammatory response might mediate the link between diabetes and COVID-19." (PMID 38455656, 2024).